APOA4 (apolipoprotein A4)
Diseases named in the same sentence as APOA4 in open-access papers (continued):
Sharing a sentence is not in itself a finding about the gene and the disease.
cancer (23 papers, 2010 to 2024). A tumor composed of atypical neoplastic, often pleomorphic cells that invade other tissues. "Apoa4 is a gene coding for an anti-inflammatory protein in intestinal epithelium, and its expression has been linked with a more differentiated cancer phenotype." (PMID 23226526, 2012). "APOA4 plays an important role in lipid metabolism and metabolic regulation, and APOA4 protein has been found to be a potential biomarker of malignant tumor differentiation in female tumor serum parameters." (PMID 37563740, 2023). "Previous studies found that APOA4 levels were markedly elevated in cancer and growing cells, in contrast to quiescent cells." (PMID 36614113, 2022). "Among the differentially expressed proteins, four factors (CNDP1, APOA4, DACH1 and BCL3) have previously been studied in different aspects of cancer, but only APOA4 and CNDP1 constitute secreted proteins." (PMID 25898255, 2015). "Another of the genes, APOA4 (Entrez gene ID: 337), has previously been identified as a potential biomarker for malignant tumor differentiation in OV." (PMID 25779658, 2015). "Furthermore, it is essential to validate the accuracy and sensitivity of LRG1 and APOA4 in larger sample cohorts, including those from patients with various types of cancer." (PMID 38735538, 2024). "Over-expression of APOA4 promotes the growth and proliferation of diverse cancer cell types." (PMID 36614113, 2022). "All of these implied that APOA4 might be a prospective target for cancer gene treatment." (PMID 36614113, 2022). "Furthermore, CNDP1 and APOA4 have been shown to be altered in plasma/serum of cancer subjects." (PMID 25898255, 2015). "It is worth noting that the expression of APOA4, GCG, CYP3A4, XPNPEP2, and FOXP3, JUN were different between cancer and normal samples in TCGA database." (PMID 32547867, 2020). "In Hp+-AG-IM network the expression of APOA4, GCG, CYP3A4, XPNPEP2 and FOXP3, JUN were statistically different in the comparison of normal and cancer in TCGA database." (PMID 32547867, 2020). "In addition, SERPINC1, APOA4, APOE and ITIH4 are described deviated in the serum of hyperplasia or cancer patients by two teams." (PMID 37091170, 2023). "Although the precise function of APOA4 in cancer is not known, APOA4 was reported to be decreased in blood of patients with various types of cancers." (PMID 29513714, 2018). "Candidates APOA4, VDBP, A1AT/SERPINA1, and SLPI were selected for initial validation and were measured by ELISA in serum samples from 89 benign and 70 malignant ovarian cancer cases, with the latter grouped into early‐stage (FIGO I and II) and late‐stage (FIGO III and IV) cancers." (PMID 25290619, 2014).
tumor (20 papers, 2010 to 2025). "Our RNA-seq data indeed identified ion transport as one of the most affected processes connected to MOXD1, and, notably, we found that the copper ion–binding protein APOA4 is up-regulated with MOXD1 overexpression in tumor cells." (PMID 38905335, 2024). "We also observed temporal changes in other key genes: lipid metabolism-associated genes such as APOA4, FABP1, and FABP2 were upregulated over time, which is consistent with reports that excess lipids promote tumor cell proliferation, colonization, and metastasis." (PMID 41009818, 2025). "However, the relationship between APOA4 expression and tumor progression remains unknown." (PMID 38584705, 2024). "In this study, using label‐free quantification, six proteins (B2MG, A1AG, HPT, CO4, APOA4, and CATC) were shown to change significantly during tumor development." (PMID 28980450, 2017).
infection (13 papers, 2011 to 2025). The state of being infected such as from the introduction of a foreign agent such as serum, vaccine, antigenic substance or organism. "Increased expression of APOA1 and APOA4 may also represent a more general response to infection." (PMID 31555604, 2019). "Specifically, the addition of FUC caused a further reduction in mRNA expression levels of NHE2, TRPV6, APOA1, APOA4, APOB, APOC3, and ASS1 compared to PEDV infection alone, while FUC supplementation counteracts PEDV-induced ARG1 upregulation." (PMID 40218394, 2025). "We also see an induction of the cell cycle marker over infection time when analyzing every cell type individually in particular in the enterocyte lineage (FABP6 and APOA4) (Fig EV2C)." (PMID 34309190, 2021). "Eight plasma proteins, including APOA4, haptoglobin, MBL1, vWF, LBP, and sCD14, were affected 6 h after infection." (PMID 31803186, 2019). "Among the early response proteins in plasma, eight showed differential abundance as early as 6 h post-infection, and these included haptoglobin, Serpin A3-6, Serpin A3-8, vWF, LBP, sCD14, MBL1, and APOA4." (PMID 31803186, 2019). "However, using receiver operating characteristic curves, we identified four to 48 candidate biomarkers of infection depending on the pathogen, including seven overlapping biomarkers (DSG2, PCBP1, MGAM, APOA4, DPEP1, GOT1, and IGFALS)." (PMID 38193073, 2023). "infections; APOA4, DPEP1, and GOT1 were negative predictors while IGFALS was a positive predictor." (PMID 38193073, 2023).
kidney disease (12 papers, 2011 to 2025). "High plasma concentrations of APOA4 have been correlated with mild-to-moderate renal failure, and may be a predictor of the progression of kidney disease." (PMID 35055195, 2022). "Our results correlate well with the data obtained by other researchers in that blood APOA4, AAT, VIL1, complement component and cytokine concentrations increased in patients with renal disorders." (PMID 32046176, 2020).
cardiovascular disease (10 papers, 2010 to 2024). "Many studies have found that low APOA4 levels are associated with arteriosclerotic cardiovascular disease." (PMID 34185819, 2021). "We found that APOA4 and TUBA1A had the same expression pattern in the three experiments and may serve as novel potential biomarkers for complications of OSA, such as cardiovascular disease, cognitive dysfunction, and male hypogonadism." (PMID 34185819, 2021).
metabolic disease (9 papers, 2015 to 2025). A congenital disorder (due to inherited enzyme abnormality) or acquired (due to failure of a metabolically important organ) disorder resulting from an abnormal metabolic process. "Afamin, ApoA4 and ApoA2 have previously been reported to be linked to the development of metabolic disease including one or more of T2D, DKD, or NASH as detailed below." (PMID 32830851, 2020). "Given the specificity of APOA4-AS in regulating apolipoprotein A4, it could be considered as a potential therapeutic target for metabolic diseases." (PMID 39273193, 2024).
adenocarcinoma (2 papers, 2022 to 2023). A common cancer characterized by the presence of malignant glandular cells. "Apolipoprotein A-IV (APOA4) and Transthyretin (TTR), which were included in random forest classifiers, were both described to be dysregulated in adenocarcinoma before." (PMID 36232544, 2022).
neurological diseases (2 papers, 2017 to 2025). "Expression alterations of APOA4, HP, and C3 proteins in OCD profile were also mentioned in other neurological diseases." (PMID 29158881, 2017).
heart disease (1 paper, 2008). "The 11q23-24 human genome location is well known for a cluster of genes (APOA1, APOC3, APOA4, and APOA5), which effect the lipid levels as well as is associated with DM and heart disease." (PMID 19038053, 2008).
APOA4 also shares sentences with these, for which no sentence is quoted: kidney failure (6 papers); allergic rhinitis (5); acute kidney injury (4); asthma (4); Glucose intolerance (4); Hypercholesterolemia (3); myocardial infarction (3); nephrotic syndrome (3); prediabetes (3); schizophrenia (3); Stroke (3); AA amyloidosis (2); airway hyperresponsiveness (2); AL amyloidosis (2); alcoholic hepatitis (2); bacterial infection (2); chronic rhinosinusitis (2); congestive heart failure (2); coronary atherosclerosis (2); endothelial dysfunction (2); fibrosis (2); hyperlipidaemia (2); kidney damage (2); liver disease (2); nasal polyps (2); neurodegenerative disease (2); prostate carcinoma (2); pulmonary fibrosis (2); renal failure (2); systemic amyloidosis (2).
A further 73 diseases each share a sentence with APOA4 in 2 papers or fewer.